INS (insulin)
Diseases named in the same sentence as INS in open-access papers (continued):
Sharing a sentence is not in itself a finding about the gene and the disease.
Allergy (69 papers, 2005 to 2026). An allergy is an immune response or reaction to substances that are usually not harmful. "Twelve of them were dropped out of the study (6 in the control and 6 in saffron groups due to moving away, loss of connection, allergy to saffron or using insulin." (PMID 31516857, 2019). "There have been numerous reports of allergies with causes such as differences in the amino acid sequences between human insulin and insulin extracted from porcine and bovine pancreas." (PMID 26838553, 2016). "For this reason, and also because of the positive result for an IgE antibody specific to human insulin, the allergy was indicated to be caused by insulin." (PMID 26838553, 2016). "In summary, our results show that airway inflammation associated with allergy influences the brain with regard to proteins involved in insulin signaling and genes involved in inflammation, as well as other functional pathways." (PMID 23915208, 2013). "Because metacresol is universally present in all current insulin preparations, we believe it has been overlooked as a possible cause of insulin allergy in some past case reports." (PMID 22937994, 2012). "In patients in whom the insulin molecule itself causes local or systemic allergies, the management of these complications becomes much more difficult." (PMID 18727824, 2008). "Components of the insulin preparation have the potential to cause allergy." (PMID 28167928, 2017). "We propose that negativity for this insulin might be due to (a) very high dosage used in this primary treatment which might have caused an adverse drug reaction, or (b) Glargine allergy-induction needs higher doses than the one used in the prick test." (PMID 25548690, 2014). "Together with our data, this suggests that systemic inflammation associated with allergy may modify insulin signaling in the brain, which could have consequences for brain function and the pathophysiology of some neurodegenerative disorders." (PMID 23915208, 2013). "Besides additives in the insulin preparation such as protamine, cresol, and phenol, the insulin molecule itself may be the cause of the allergy." (PMID 18727824, 2008). "Insulin allergy remains a rare yet challenging condition that requires careful diagnostic evaluation." (PMID 42255890, 2026). "This potential for immunogenicity can complicate the use of gelatin in insulin delivery, particularly for patients with sensitivities or allergies to animal-derived products." (PMID 40352348, 2025). "Suspicion of an allergy to insulin injections requires the detection of specific IgE antibodies to insulin in the patient’s serum or plasma, as well as skin tests (skin prick tests or intradermal tests)." (PMID 41179869, 2025). "The WoSCC database timeline viewer showed the top five clusters as insulin resistance, gut-brain axis, allergy, vaginal microbiome, and necrotizing enterocolitis." (PMID 41450934, 2025). "Namely, a sulfhydryl compound like ALA can help dissociate S-S bonds within insulin molecules and expose specific insulins’ amino acid sequence (Ile-Leu-Gln), which acts as an antigen, thereby provoking an allergic reaction." (PMID 39065589, 2024). "Skin reactions caused by insulin therapy: lipohypertrophy (most common manifestation, at the site of insulin injection), lipoatrophy, erythema, local infections, subcutaneous nodules, allergies." (PMID 37606477, 2023). "The development of rash after detemir initiation and rapid progression to DKA suggests an aberrant immune response leading to the insulin allergy and antibody-induced interference with insulin analogues." (PMID 35350098, 2022). "About one-third of cases of allergy are due to insulin itself and the rest are related to the components of insulin formulation, that is, zinc protamine and meta-cresol." (PMID 35722152, 2022). "Our case highlights the importance of diagnosing insulin allergy through a detailed history and focused testing." (PMID 34325725, 2021).
Allergy (continued). "Other rarer causes included too early donation, thrombocytosis, polycythemia, pancytopenia, malaria, allergies, insulin, and tuberculosis." (PMID 32082957, 2020). "Other rarer causes included early donation, thrombocytosis, polycythemia, pancytopenia, malaria, allergies, insulin, and tuberculosis." (PMID 32082957, 2020). "Other less common causes include early donation, thrombocytosis, polycythemia, pancytopenia, malaria, allergies, insulin, and tuberculosis." (PMID 32082957, 2020). "Two hundred thirty (95.0%) answered that the complications of insulin therapy are low blood sugar, insulin allergy, insulin resistance, and wasting of subcutaneous tissue." (PMID 31915711, 2019). "The data to be input into the diseases, insulin, medication, and allergy menus (eg, entering the whole name and dose of the medication and selecting the insulin injection site) are more complicated than in other functions." (PMID 29631989, 2018). "Items that showed a decreasing pattern were diseases, insulin, medication, and allergy, belonging to the Medication management and My Chart menus." (PMID 29631989, 2018). "Linking PHR data would reduce the inconvenience to users of inputting data for diseases, insulin, medication, and allergy." (PMID 29631989, 2018). "Because a change in his insulin treatment was inefficient, treatment with liraglutide to protect residual insulin secretion was started, resulting in improvements in his insulin allergy, serum glycated hemoglobin, insulin, and eosinophil levels." (PMID 27456688, 2016). "When insulin allergy is present, cross-antigenicity with numerous insulin formulations occurs, as in the case of the present patient." (PMID 26838553, 2016). "Currently, treatment options for insulin allergy include switching to another insulin device, steroid therapy, continuous subcutaneous insulin infusion therapy, hyposensitization therapy, pancreas transplantation, and anti-IgE therapy." (PMID 27456688, 2016). "In our case, it is possible that both the insulin allergy and the presence of anti-insulin IgG antibodies themselves aggravated our patient’s glycemic control." (PMID 27456688, 2016). "Type I allergy reactions are IgE-dependent, induced by the insulin molecule or other components, activating the allergy-related pathway." (PMID 25548690, 2014). "Previous case reports have suggested that insulin-related allergy depends on dosage, route of administration, and type of insulin and these account for discrepancies observed between allergenic crisis and skin testing." (PMID 25548690, 2014). "Given the escalating insulin allergy events observed, a desensitization protocol was planned with Glargine, a long-lasting insulin formulation that is easily available in the country." (PMID 25548690, 2014). "The observed decrease in levels of the phosphorylated form of this receptor upon allergy suggests an allergy-induced inhibition of insulin signaling in the brain." (PMID 23915208, 2013). "We have analyzed gene expression in mouse brains and found that allergy led to changes in the genes and/or proteins involved in the insulin-signaling pathway, in inflammatory pathways and in other pathways." (PMID 23915208, 2013). "Next, Novo NordiskTM diluting fluid can be helpful to distinguish an excipient allergy from true insulin and/or aspart allergy." (PMID 22937994, 2012). "In the past, the diagnosis of insulin allergy was facilitated by commercially available insulin allergy test kits." (PMID 22937994, 2012). "We present the case of a 12-year-old Caucasian girl with localized allergy to the insulin excipient metacresol, and the subsequent desensitization therapy using continuous subcutaneous insulin infusion with simultaneous intravenous insulin infusion." (PMID 22937994, 2012). "Some of the rarer allergies included seminal fluid, celery, various medications (including porcine and human recombinant insulin, Hydroxocobalamin, and Fluoxetine), goat, yoghurt, and Pudu." (PMID 21190546, 2010).
Allergy (continued). "In a previously published study, Vianna and Garcia-Leme have demonstrated that insulin modulates leukocyte migration into the airways during the course of the allergic reaction." (PMID 20667094, 2010). "Since human insulin and its analogues have been introduced, insulin allergies are rare and currently reported in only 0.1% to 2% of all patients treated with insulin." (PMID 18727824, 2008). "Successful treatment of allergies due to insulin preparations has been reported during the last few years." (PMID 18727824, 2008). "Successful treatment of insulin allergies has been reported using a continuous subcutaneous pump infusion of insulin, switching from human insulin to insulin aspart or lispro, or in severe cases, by pancreas transplantation." (PMID 18727824, 2008). "Multiples cases of allergy to insulin components have been described and reported since it is the treatment for type I diabetic patients." (PMID 16375762, 2005). "Many algorithms of insulin allergy diagnosis have been published although diagnosis is merely based in compatible clinical history and skin test since many diabetic patients can have positive skin test and serum antibodies without clinical symptoms." (PMID 16375762, 2005). "Insulin allergy is rare but challenging for diabetic patients." (PMID 41179869, 2025). "Additionally, long-term insulin use can lead to side effects such as the development of insulin antibodies and insulin allergy." (PMID 40429740, 2025). "However, although the emergence of recombinant insulin preparations has largely eliminated the-once-common insulin allergies, the results of our study showed that more attention should be paid to this issue." (PMID 38813039, 2023). "In the past, allergy was another frequent adverse effect in patients receiving insulin therapy." (PMID 37143729, 2023). "Some of the side effects are allergy-related, especially to insulin intake." (PMID 35722152, 2022). "Diabetics receiving protamine-containing insulin formulations are known to develop an allergy to protamine due to the production of IgE antibodies, and are 40 to 50-fold more likely to develop acute adverse events when administered the peptide for heparin reversal." (PMID 35812346, 2022). "Therapeutic options in patients with insulin allergy can thus be challenging." (PMID 34325725, 2021). "Furthermore, the treatment of these rats with insulin injection recovered the atopic response, confirming that insulin plays a central role in allergy." (PMID 32708186, 2020). "In this patient, SIA caused an allergic reaction, in contrast to continuous IV insulin infusion for which allergic symptoms did not appear." (PMID 31711488, 2019). "A 40 mg dose of methylprednisolone sodium succinate and 10 mg of diphenhydramine were given in the event of the possible occurrence of a severe allergic reaction, and continuous IV infusion of recombinant human insulin was initiated at a rate of 0.1 units/kg/hour." (PMID 31711488, 2019). "Within the set of negatively-regulated genes in chronically insulin-treated cells we sought patterns that could reveal gene sets that are targets for the suppression of SG formation, a potential anti-allergy strategy." (PMID 29430572, 2017). "However, the availability of genetically recombinant human insulin formulations has led to insulin allergy becoming uncommon, and such allergies also occur much more rarely when insulin analog formulations are administered." (PMID 26838553, 2016). "Although the formation of non-neutralizing antibodies is rarely observed with recombinant human insulin, an allergy may still occur in some patients due to the preservatives used in insulin preparations." (PMID 26983499, 2016). "The reasons why the allergic reaction is alleviated when insulin glulisine is used may be suggested as follows." (PMID 26838553, 2016).
Allergy (continued). "Notably, reduced IDE levels have been found in the brains of AD patients and in mouse models of AD, thus rendering a potential link between allergy, insulin-related deficits and AD." (PMID 23915208, 2013). "As reported in this case, desensitization with subcutaneously administered human insulin using an ultra-rush protocol in patients with an insulin allergy may present an easy form of therapy that is successful within a few days." (PMID 18727824, 2008). "Following negative allergy testing to various insulin prep additives such as zinc, a type III hypersensitivity reaction was determined to be causative." (PMID 39622650, 2024). "Patients with documented fish or insulin-neutral protamine hagedorn insulin (NPH) allergies or patients have undergone a vasectomy should not receive protamine." (PMID 36827672, 2023). "It is found that there are 50 potential targets of PLP in allergy, which were imported into the String database to establish PPI, among which the top 5 interaction relationships according to the number are: INS, TNF, CAT, MAPK1 and VEGFA." (PMID 35879791, 2022). "None of the allergic reactions in either study was considered related to the investigational insulin and none was suspected to be AIA mediated." (PMID 29355435, 2018). "Because the Novo NordiskTM diluting fluid does not contain insulin but does have similar excipients to insulin aspart, a negative result would strongly suggest an allergic reaction to aspart and not to an excipient, whereas a positive result would indicate an excipient allergy." (PMID 22937994, 2012).
obstructive sleep apnea (62 papers, 2010 to 2026). "NS is also a recognized risk factor for obstructive sleep apnea, which contributes to insulin resistance and systemic inflammation via intermittent hypoxia-induced oxidative stress and sympathetic activation." (PMID 41155098, 2025). "The variables associated with one-year postoperative %TWL were obstructive sleep apnea, osteoarthritis, insulin treatment, preoperative weight, insulin resistance index, apolipoprotein A, uric acid, complement component 3, and vitamin B12." (PMID 38927382, 2024). "In patients with obstructive sleep apnea, sleep loss concomitant with the hyperactivation of the sympathetic nervous system and intermittent hypoxia results in oxidative stress, inflammation, adipokine changes, and insulin resistance, increasing the risk of T2DM." (PMID 34869629, 2021). "Both short sleep duration and obstructive sleep apnea (OSA) seem to be associated with insulin resistance." (PMID 32546151, 2020). "The underlying mechanisms include sympathetic overactivity during the night-time period, endothelia dysfunction, insulin resistance, volume overload and sleep-disordered breathing in patients with obstructive sleep apnea." (PMID 40868938, 2025). "Obstructive sleep apnea (OSA) can cause failure to thrive, behavioral issues, decreased intellectual function, and an increased risk of cardiovascular morbidity, insulin resistance and weight gain in children." (PMID 36553418, 2022). "We aimed to analyze changes in the apnea–hypopnea index and selected cardio-metabolic parameters (total cholesterol, triglycerides, glucose, insulin, blood pressure) in relation to the reduction in body mass index in obstructive sleep apnea patients." (PMID 33918454, 2021). "Individuals with obstructive sleep apnea should also benefit from a screening for MAFLD since it was proved that this condition strongly suggests insulin-resistant MAFLD." (PMID 34944682, 2021). "Intermittent hypoxia (IH) is a hallmark of obstructive sleep apnea (OSA) and induces metabolic dysfunction manifesting as inflammation, increased lipolysis and insulin resistance in visceral white adipose tissues (vWAT)." (PMID 33383883, 2020). "Background and objectives: Obstructive sleep apnea syndrome (OSAS) is associated with cardiovascular and metabolic risk factors, such as insulin resistance." (PMID 31137600, 2019). "Obese patients often have an unhealthy lifestyle, obstructive sleep apnea, insulin resistance, and sympathetic nervous system activation status, which are also related to thrombotic adverse events." (PMID 25848965, 2015). "Previous small-scale clinical studies have found that patients with obstructive sleep apnea syndrome (OSAS) who receive continuous positive airway pressure (CPAP) treatment can improve insulin resistance, oxidative stress, and inflammatory responses, thereby reducing CVD risk." (PMID 38327493, 2024). "Baseline values of estimated glomerular filtration rate and plasma concentrations of acute kidney injury biomarkers, glucose, insulin, non‐esterified fatty acids, and triglycerides in individuals with obstructive sleep apnea and healthy controls before 6 h of normoxia and intermittent hypoxemia." (PMID 37653582, 2023). "Furthermore, glucose metabolism can be negatively impaired by sleep issues such as obstructive sleep apnea (OSA), which causes insulin resistance and alters glucose metabolism." (PMID 26166263, 2015). "Moreover, in patients with obstructive sleep apnea syndrome, plasma vaspin levels were associated with BMI, WC, WHpR and NC as well as total triglyceride and insulin levels, but not with HC." (PMID 40140188, 2025). "Intermittent hypoxemia (IH), a pathophysiologic consequence of obstructive sleep apnea (OSA), adversely affects insulin sensitivity, insulin secretion, and glucose tolerance." (PMID 39763275, 2025).
obstructive sleep apnea (continued). "Obstructive sleep apnea (OSA) can lead to metabolic dysfunction in the tonsil tissue, resulting from the intermittent hypoxia, which alters the insulin sensitivity and inflammation signaling." (PMID 40724870, 2025). "The underlying mechanisms of the association between obstructive sleep apnea (OSA) and reduced insulin clearance remain not completely understood." (PMID 40365648, 2025). "Because VAT is more sensitive to lipolysis and more insulin-resistant than SAT, this can have impacts on overall insulin resistance and the development of cardiovascular conditions, diabetes, and obstructive sleep apnea (OSA)." (PMID 39235730, 2024). "His medical history includes seizure disorder, obstructive sleep apnea (OSA), MDD, insomnia, generalized anxiety disorder (GAD), and type 2 diabetes mellitus managed with insulin." (PMID 39347226, 2024). "In another study on patients with moderate-to-severe obstructive sleep apnea, CPAP therapy improve insulin secretion capacity; reduce total cholesterol, low-density lipoprotein and leptin levels." (PMID 35755912, 2022). "Barrett’s esophagus patients may be more likely to have obstructive sleep apnea than GERD patients without BE due to insulin/insulin growth factor pathways which may have a role in the development of BE; obstructive sleep apnea is associated with insulin resistance." (PMID 23663216, 2013). "A study involving 40 adults with moderate to severe obstructive sleep apnea revealed that short‐term continuous positive airway pressure treatment improved insulin sensitivity only in the nonobese subgroup." (PMID 38599827, 2024). "Besides, increased insulin was observed in morbidly obese subjects with obstructive sleep apnea but not in morbidly obese individuals without such a sleep-related disorder." (PMID 25944984, 2015).